STAT3 (signal transducer and activator of transcription 3)
Diseases named in the same sentence as STAT3 in open-access papers (continued):
Sharing a sentence is not in itself a finding about the gene and the disease.
cervical carcinoma (continued). "A cervical cancer tissue microarray study has shown that constitutive activation of STAT3 correlates with the progression of HPV positive cervical cancer." (PMID 27824155, 2016). "STAT3 is one of the oncogenic transcription factors constitutively activated in cervical cancer cells." (PMID 27824155, 2016). "The JAK2/STAT3 pathway has been reported to play a crucial role in regulating the progression of cervical cancer." (PMID 26219895, 2016). "Another EMT-related cytokine, interleukin-6 induced EMT through signal transducer and activator of transcription 3 in human cervical carcinoma." (PMID 25590298, 2015). "Clinically, STAT3, the expression of which, predicted poorer outcome, was inversely correlated with miR-125a in cervical cancer." (PMID 26389681, 2015). "Additional experiments showed that IL-6 exposure in cervical carcinoma cell lines induced IL-6R and STAT3 expression, promoted cell growth, and altered cell morphology." (PMID 25590298, 2015). "In order to confirm the functional effect of STAT3 activation on apoptosis of cervical cancer cell lines, TUNEL assays were carried out and we observed that there is a direct correlation between the induction of antiapoptotic genes and apoptosis." (PMID 26346346, 2015). "Our data suggests that STAT3 is an important signaling pathway activated by PRL in cervical cancer cells and it modulates the induction of antiapoptotic genes." (PMID 26346346, 2015). "Functional studies showed that miR-125a overexpression significantly suppressed the growth, invasion and epithelial-mesenchymal transition (EMT) of cervical cancer cells both in vitro and in vivo via decreasing STAT3 expression." (PMID 26389681, 2015). "With activated STAT3, IL-6 emerges senescent at early passages in cervical cancer tissues infected with high-risk HPV and activates the STAT3 and cellular senescence." (PMID 26308848, 2015). "Activation of the STAT3 pathway is required for IL-6-induced EMT in the progression of human cervical carcinomas." (PMID 25638155, 2015). "STAT3 induction in cervical cancer cell lines was the only pathway that showed activation after PRL stimulus compared to HaCaT." (PMID 26346346, 2015). "Indirect inhibition of miR-21 by targeting STAT3 or its direct inhibition using specific hairpin inhibitor reduced viability of cervical cancer cells and resulted in a dose-dependent accumulation of PTEN." (PMID 25539644, 2014). "A strong correlation of active STAT3 with levels of E6/E7 in cervical cancer lesions, and specific silencing of STAT3 resulting in abrogated E6 expression in cervical cancer have been observed earlier." (PMID 25539644, 2014). "To test the STAT3-mediated regulation of miR-21, first we performed in vitro silencing of STAT3 expression in cervical cancer cells, SiHa, using siRNA against STAT3." (PMID 25539644, 2014). "We observed that STAT3 expression and specifically its activation were decreased in response to Let-7a restoration in cervical cancer which is indicative of a negative regulation of STAT3 by Let-7a in cervical cancer cells." (PMID 25539644, 2014). "Given the reduced activities of Wnt, Notch and STAT3 signaling in resveratrol-treated cervical cancer cells, it would be worthwhile to evaluate the significance of Wnt, Notch or STAT3 signaling for CC cells and the biological consequence of their inhibition." (PMID 25061499, 2014). "Inhibitory effect of silencing STAT3 signaling on miR-21 and cell viability demonstrates a potential role of active STAT3 and over-expressed miR-21 in survival and growth of cervical cancer cells." (PMID 25539644, 2014). "Aberrantly expressed and constitutively active STAT3 signaling plays a pivotal role in initiation and progression of cervical cancer and controls expression of viral oncogenes, E6 and E7 during cervical carcinogenesis." (PMID 25539644, 2014).
cervical carcinoma (continued). "STAT3 activation was found to predict a worse clinical outcome in many other types of cancer, such as cervical cancer, esophageal squamous cell carcinoma, head and neck squamous cell carcinoma and thymic epithelial cancer." (PMID 24995504, 2014). "Results presented in this article demonstrate for the first time a relation between miR-21 and Let-7a in HPV E6-mediated active STAT3 signaling in cervical cancer cells." (PMID 25539644, 2014). "A high level of constitutively active STAT3 is a characteristic feature of many epithelial cell malignancies that include cervical cancer." (PMID 25539644, 2014). "These alterations were associated with loss of active STAT3, increase in PTEN level and reduced viability of cervical cancer cells." (PMID 25539644, 2014). "Constitutive activation of STAT3 plays a prominent role in the development and progression of cervical cancer." (PMID 25268165, 2014). "Leads obtained from the present study provide a strong rationale for developing novel STAT3-based approaches for therapeutic interventions against HPV infection to control cervical cancer." (PMID 23874455, 2013). "Further, we investigated growth inhibitory events following inhibition of STAT3 phosphorylation by curcumin and AG490 that were associated with abrogated E6, E7 expression in HPV16 positive cervical cancer cells." (PMID 23874455, 2013). "To test the functional relevance of active STAT3 in the expression of HPV16 oncogenes we performed in vitro silencing of STAT3 in cervical cancer cells using siRNA against STAT3." (PMID 23874455, 2013). "Together, these findings indicate that constitutive activation of STAT3 is a frequent occurrence in high grade malignant cervical carcinomas and positively correlated with poorer histopathological grades." (PMID 20977777, 2010). "To determine its correlation we examined STAT3 expression in HPV16+ cervical cancer cases with different histopathological grades." (PMID 20977777, 2010). "Recent observations indicate potential role of transcription factor STAT3 in cervical cancer development but its role specifically with respect to HPV infection is not known." (PMID 20977777, 2010). "Immunoblot analysis of cellular proteins demonstrated constitutive STAT3 expression in all cervical cancer cell lines although the degree of expression was variable." (PMID 20977777, 2010). "We observed a constitutively active STAT3 in cervical cancer cases which increased as a function of disease severity." (PMID 20977777, 2010). "We demonstrate that in the presence of HPV16, STAT3 is aberrantly-expressed and constitutively-activated in cervical cancer which increases as the lesion progresses thus indicating its potential role in progression of HPV16-mediated cervical carcinogenesis." (PMID 20977777, 2010). "In the present study, we demonstrate aberrantly expressed and constitutively active STAT3 both in cervical cancer cell lines and in cervical precancer and cancer lesions." (PMID 20977777, 2010). "Transfection of siRNA against Stat3 into cervical cancer cell line, SKG II, induced the inhibition of expression of pStat3." (PMID 19638983, 2009). "Only one immunohistochemical study has been reported on p-Stat3 expression in cervical cancer, in which the researchers reported that 25 specimens (24.0%) showed positive immunoexpression of p-Stat3 in 104 cervical cancer specimens." (PMID 19638983, 2009).
cervical carcinoma (continued). "In conclusion, p-Stat3 immunoexpression was found to be a potent prognostic factor of cervical cancer." (PMID 19638983, 2009). "Expression of p-Stat3 in all five cervical cancer cell lines was confirmed by western blotting analysis (data not shown)." (PMID 19638983, 2009). "Past research has showed similar cytoxicity using a dominant negative STAT3 and STAT3 inhibitors in cervical cancer cell lines expressing increased p-STAT3." (PMID 18939993, 2008). "The elevated levels of Stat3 phosphorylation were detected in 25.2% of 107 total cervical cancer specimens as well as three out of four human cervical cancer cell lines." (PMID 17311011, 2007). "This is the first study to demonstrate that Stat3 is activated in human endometrial and cervical cancer tissues." (PMID 17311011, 2007). "In summary, our results demonstrated for the first time that Stat3 phosphorylation is elevated in clinical human endometrial and cervical cancer samples." (PMID 17311011, 2007). "This is consistent with previous results that HT-3 cervical cancer cell line expressed elevated levels of Stat3 phosphorylation." (PMID 17311011, 2007). "We examined tyrosine phosphorylation of Stat3 (activated form of Stat3) in multiple endometrial and cervical cancer tissues using tissue microarray slides as well as cancer cell lines to explore the possible activation of Stat3." (PMID 17311011, 2007). "Immunohistochemistry was carried out to detect the expression of p-Stat3 (Ser727), Bcl-xL, survivin, and Mcl-1 in both endometrial and cervical cancer tissues." (PMID 17311011, 2007). "Our results demonstrated that elevated levels of phosphorylation (Tyr705) of Stat3 protein were detected in the nuclei of 25 out of 104 total cervical cancer specimens." (PMID 17311011, 2007). "Cell growth of cervical cancer cells with elevated p-Stat3 (Tyr705) was differentially suppressed in the presence of dnStat3." (PMID 17311011, 2007). "Our results indicated that elevated levels of phosphorylation of Stat3 protein at Tyr residue 705 and serine residue 727 (Ser727) were detected in endometrial and cervical cancer specimens." (PMID 17311011, 2007). "We observed that Stat3 is activated in cervical cancer early stages such as Stage 1, suggesting that Stat3 is a target of chemoprevention in cervical cancer." (PMID 17311011, 2007). "We also examined the phosphorylation of Stat3 in human endometrial cancer cell lines, Ishikawa, RL-95-2, Hec-1B, and cervical cancer cell lines, C33A, HeLa, SiHa and HT-3." (PMID 17311011, 2007). "Expression of a dominant-negative Stat3 mutant using adenovirus-mediated gene transfer inhibited cell growth and induced apoptosis in HeLa and SiHa cervical cancer cell lines expressing elevated levels of Stat3 phosphorylation." (PMID 17311011, 2007). "Our results also showed that elevated levels of phosphorylation of Stat3 protein were detected in the endometrial and cervical cancer specimens." (PMID 17311011, 2007). "Stat3 appears to be one of the oncogenic pathways activated in human endometrial and cervical cancers." (PMID 17311011, 2007). "Additionally, IL-6 secreted by HPV-positive cervical cancer cells induces STAT3 activation in neighboring HPV-negative cervical cancer cells, thereby enhancing cancer cell proliferation." (PMID 41488475, 2025). "Similarly, in cervical cancer, STAT3-miR-223 regulates HMGCS1 expression, influencing disease progression." (PMID 40642530, 2025). "Furthermore, it has been observed that the activation of STAT3 factor is correlated with HPV infection in a group of cervical cancers." (PMID 40729003, 2025). "First, we assessed whether the cellular expression of CD204+ or CD163+ M2‐TAM correlated with the STAT3/NF‐κB signaling pathways in the tumor microenvironment (TME) of 95 patients with cervical cancer." (PMID 41263059, 2025).
cervical carcinoma (continued). "Conversely, senescent fibroblasts secrete elevated levels of inflammatory cytokines (including IL-6), which further activate STAT3 in an autocrine manner and regulate the tumor microenvironment, thus resulting in resistance and recurrence of cervical cancer after radiotherapy." (PMID 38651153, 2024). "In addition, we also demonstrated that recombinant IL-6 and IL-8 proteins can promote the phosphorylation of Jak-2 and Stat3 in cervical cancer cell lines, and anlotinib can neutralize this promoting effect." (PMID 39193386, 2024). "In addition, STAT3 is a downstream molecule of lncRNA NEAT1, which can positively regulate STAT3 cell levels by reducing ubiquitination levels, ultimately promoting the growth and metastasis of cervical cancer tumors or accelerating RA progression." (PMID 38172648, 2024). "Persistent activation of STAT3 has been found in various cancer types, including cervical cancer." (PMID 39201624, 2024). "Additionally, STAT3 signaling pathways have been reported to stimulate cervical cancer cell metastasis by facilitating EMT progression and upregulating the expression of ECM degradation enzymes, including MT1-MMP, uPA, and uPAR." (PMID 39273231, 2024). "In this context, we hypothesized that M2-TAMs and via STAT3/NF-κB crosstalk can modulate important hallmarks of tumor progression, negatively affecting the survival of 691 patients with cervical cancer." (PMID 39061137, 2024). "It has also been reported that PRL may regulate anti-apoptotic gene induction via STAT3 activation in cervical cancer cells." (PMID 38276281, 2024). "Therefore, we can confidently conclude that the activation of the JAK/STAT3 signaling pathway regulated by LINC00518 enhances cell growth in cervical cancer." (PMID 39108268, 2024). "Similarly, upon downregulation of LINC00518 expression, the protein levels of p-JAK2 and p-STAT3 decreased in HeLa cervical cancer cells as well." (PMID 39108268, 2024). "In this study, we found that IL-6 and IL-8 could promote the phosphorylation levels of Jak-2 and Stat3 proteins in cervical cancer cells." (PMID 39193386, 2024). "Interestingly, our results showed a strong association correlation between CD163 + CD204 + M2TAM, via STAT3/NF-κB pathways and the expression of CD25, FOXP3, MIF, and IL-17 in 56.2%, 76.3%, 85.2%, and 86.1%, respectively, of 691 patients with cervical cancer." (PMID 39061137, 2024). "Increased STAT3 expression was noted in cervical cancer tissue." (PMID 37784183, 2023). "Thus, LINC00240 significantly downregulates miR-124-3p, decreases MICA mRNA and protein expressions and reduces the cytotoxic activity of NKT cells by regulating STAT3 promoted cervical cancer progression in vitro and in vivo." (PMID 37784183, 2023). "In addition, PGG suppressed the STAT3 expression in HeLa cervical cancer cells, thereby decreasing cell viability and increasing the cleaved PARP concentrations." (PMID 37375411, 2023). "Importantly, they showed miR-125a increased sensitivity of cervical cancers to paclitaxel and cisplatin by decreasing STAT3." (PMID 36902166, 2023). "Prior studies proved that STAT3 promotes the proliferation and migration abilities of cervical cancer cells, and then whether STAT3 influence the autophagy of cervical cancer cell remains unclear." (PMID 35057825, 2022). "Furthermore, it has been reported that MUC16 promotes proliferation and invasion via activation of the JAK2/STAT3 pathway in cervical cancer." (PMID 36199046, 2022). "In cervical cancer, STAT3 was overexpressed and negatively correlated with LC3B level." (PMID 36499030, 2022). "Furthermore, IL-6 is also essential for the proliferation of HPV-positive cervical cancer cells via STAT3 activation." (PMID 36310590, 2022). "Apart from NF-κB, the signal transducer and activator of transcription 3 (STAT3) may also be involved in cervical cancer development, particularly in the transformation of precancerous cervical lesions into cancer." (PMID 36230832, 2022).
cervical carcinoma (continued). "We found that STAT3 is negatively related to LC3B in 46 cervical cancer patients." (PMID 35057825, 2022). "Collectively, our findings suggest that STAT3 inhibition may be a novel therapeutic option for treating cervical cancer patients." (PMID 36551576, 2022). "In this study, we found that the level of autophagy increased significantly after STAT3 knockout or knockdown in cervical cancer cells by detecting the protein expression levels of Bcl-2 and Beclin-1, it was found that the expression of Bcl-2 decreased, while the expression of Beclin-1 increased." (PMID 35057825, 2022). "STAT3 knockout or knockdown significantly increased the autophagy level and decreased proliferation, migration, plate colony formation and subcutaneous tumorigenesis of cervical cancer cells in vitro and in vivo." (PMID 35057825, 2022). "Oncostatin M (OSM), a pleiotropic cytokine, induces STAT3 activation, exacerbating cervical cancer." (PMID 36551576, 2022). "Therefore, a series of in vitro experiments have proven that STAT3 plays an indispensable role in the proliferation, metastasis and colony formation of cervical cancer cells." (PMID 35057825, 2022). "This indicates that STAT3 may be an important prognostic and therapeutic target for cervical cancer." (PMID 35057825, 2022). "Thus, the increased activation of the STAT3 pathway is a crucial cellular process linking chronic inflammation to cervical cancer development." (PMID 35164678, 2022). "Our findings suggest that the OSM-STAT3 axis regulates key transcriptional and epigenetic programs and that the inhibition of STAT3 may be a novel treatment for cervical cancer patients." (PMID 36551576, 2022). "It was confirmed that the autophagy level of cervical cancer cells increased after the downregulation of STAT3, which may play a role through the Bcl2-Beclin1 axis." (PMID 35057825, 2022). "Therefore, understanding the gene regulation mechanism mediated by STAT3 in cervical cancer is important for the development of innovative drugs that can directly or indirectly inhibit STAT3." (PMID 36551576, 2022). "Overall, our findings suggest that the hypoxia-related genes, including NDRG1, HK2, and PLOD2, can be controlled by inhibiting STAT3, and this strategy is a novel therapeutic option that may effectively reduce the progression of cervical cancer." (PMID 36551576, 2022). "Besides, the expression of STAT3 in cervical cancer is higher than that in normal cervical tissues and precancerous lesions, and the expression of STAT3 in cancer tissues is related to the clinical stage, which also proves our results." (PMID 34165442, 2021). "The root extract of P. patens exhibited strong inhibition of several signaling pathways in HeLa cells, a cervical cancer cell line, and was found to be the most potent in inhibiting the activation of Stat3, Smad, AP-1, NF-κB, MYC, Ets, Wnt and Hdghog, at a concentration of 40 μg/mL." (PMID 34017038, 2021). "We have demonstrated through in vitro and in vivo experiments that Bazedoxifene blocks the activation of STAT3 in cervical cancer, which can inhibit cervical cancer growth and affect EMT signaling and apoptosis associated with cancer cell migration and invasion." (PMID 34445405, 2021). "The expression of STAT3 has been proposed as a poor prognostic factor in cervical cancer." (PMID 33671013, 2021). "Moreover, up-regulation of PAR2 (F2RL1) induces the proliferation of cervical cancer cells by activating STAT3, which is consistent with our current results that overexpression of F2RL1 was involved in the JAK/STAT signaling pathway." (PMID 33671013, 2021). "Therefore, it is necessary to study the inhibition of STAT3 in HPV-positive cervical cancer cells, which was the focus of this study." (PMID 34445405, 2021).